GRK2 (G protein-coupled receptor kinase 2)
Diseases named in the same sentence as GRK2 in open-access papers (continued):
Sharing a sentence is not in itself a finding about the gene and the disease.
dengue (1 paper, 2012). "We found that GRK2 was a host factor needed for productive infection by yellow fever, dengue and hepatitis C viruses and was required for both viral entry and efficient replication of the viral genome." (PMID 23029581, 2012). "It would be then interesting to test if RPLP1 and RPLP2 knockdowns affect the luciferase activity from the dengue replicon at late time points, as observed upon GRK2 knockdown." (PMID 23029581, 2012).
diabetic nephropathy (1 paper, 2024). "Blocking the prostaglandin E2 (PGE2)‐EP1‐Gaq‐Ca2+ signal pathway in glomerular mesangial cells (GMCs) by internalizing prostaglandin E2 receptor 1 (EP1) with GRK2 may be a potential treatment for diabetic nephropathy (DN)." (PMID 39438268, 2024).
diabetic neuropathy (1 paper, 2018). A chronic, pathological complication associated with diabetes mellitus, where nerve damages are incurred due to diabetic microvascular injury involving small blood vessels that supply these nerves, resulting in peripheral and/or autonomic nerve dysfunction. "Such regulators might include the HCN2 channel, which regulates nociceptive sensitivity during diabetic neuropathy and/or GRK2, which regulates duration of acute sensitization responses." (PMID 29752280, 2018).
Flavivirus Infections (1 paper, 2012). Infections with viruses of the genus FLAVIVIRUS, family FLAVIVIRIDAE. "Together, our findings identified GRK2 as a novel regulator of flavivirus infection and suggest that inhibition of GRK2 function may constitute a new approach for treatment of flavivirus associated diseases." (PMID 23029581, 2012).
gallbladder tumor (1 paper, 2017). "Taken together, these data suggest that eIF3d promotes gallbladder tumor growth and migration at least partially through regulating GRK2 activity, which in turn leads to activation of PI3K/AKT signaling pathways." (PMID 28594409, 2017).
Graves disease (1 paper, 2025). Graves' disease is an autoimmune disorder that leads to overactivity of the thyroid gland (hyperthyroidism).It is caused by an abnormal immune system response that causes the thyroid gland to produce too much thyroid hormones. "In AIH, it regulates Treg cell function through the PI3K-Akt pathway, and in Graves' disease, GRK2 activity is increased by TSH receptor (TSHR)–specific autoantibodies, exacerbating the autoimmune response." (PMID 40224487, 2025).
hyperlipidaemia (1 paper, 2013). "Based on these findings, it might be expected that targeted GRK2+/− deletion would lead to enhanced chemokine signalling which would propagate inflammatory cell recruitment in vivo and augment atherosclerotic lesion formation in GRK2+/− mice with hyperlipidaemia." (PMID 23690662, 2013).
ischemic heart disease (1 paper, 2022). "Our lab has previously shown that cardiomyocyte overexpression of GRK2 has a detrimental effect on cardiac function, hypertrophy, and remodeling in ischemic heart disease." (PMID 33560342, 2022).
Jeune syndrome (1 paper, 2020). Jeune syndrome, also called asphyxiating thoracic dystrophy, is a short-rib dysplasia characterized by a narrow thorax, short limbs and radiological skeletal abnormalities including "trident" aspect of the acetabula and metaphyseal changes. "Loss of GRK2 deregulates the function of two major morphogens in the bone ‐ Hedgehog and canonical Wnt signaling, and manifests in autosomal recessive skeletal ciliopathy syndrome, asphyxiating thoracic dystrophy or Jeune syndrome." (PMID 33200460, 2020).
kidney damage (1 paper, 2024). "In the long run, there appears to be promising research potential regarding the therapeutic impact of these inhibitors on nephropathy caused by elevated GRK2." (PMID 39438268, 2024).
lymphopenia (1 paper, 2020). Reduction in the number of lymphocytes. "GRK2‐mediated phosphorylation of S1P1 is also a requisite step for lymphopenia induced by S1P1‐desensitizing agents." (PMID 32810927, 2020).
ovarian carcinoma (1 paper, 2016). A malignant neoplasm originating from the surface ovarian epithelium. "We found three kinases (CAMK2N1, GRK2, and MAP3K9) to be KGDs in OCC models, compared to other ovarian cancer histologies such as serous ovarian cancer." (PMID 26947069, 2016).
Pain (1 paper, 2015). An unpleasant sensory and emotional experience associated with actual or potential tissue damage, or described in terms of such damage. "Previous work has shown that the level of GRK2 was significantly decreased in chronic neuropathic pain and inflammatory pain." (PMID 26064176, 2015).
parasitic infection (1 paper, 2021). "In S. mansoni, this G-protein coupled receptor kinase 2 may stimulate sporocyst expansion or renewal into snail host tissues (i.e. new generation of daughter sporocysts) while escaping host immune defenses, to maintain the parasitic infection and eventually, cercarial production." (PMID 34167443, 2021).
Parkinsonism (1 paper, 2025). Characteristic neurologic anomaly resulting from degeneration of dopamine-generating cells in the substantia nigra, a region of the midbrain, characterized clinically by shaking, rigidity, slowness of movement and difficulty with walking and gait. "This is the first report linking a point mutation in FMR1 to parkinsonism, demonstrating that the FMRP-P608L mutation impairs the D1R pathway by reducing its binding to GRK2." (PMID 40980401, 2025).
pulmonary regurgitation (1 paper, 2019). "mRNA levels for β-adrenoceptors and G-protein coupled receptor kinases GRK2, GRK3 and GRK5 in peripheral blood mononuclear cells from patients with pulmonary regurgitation under treatment (n = 9) or not (n = 14) with betablockers." (PMID 30837872, 2019).
schizophrenia (1 paper, 2025). A major psychotic disorder characterized by abnormalities in the perception or expression of reality. "Furthermore, we identified six genes—GRK2, KLF3, TAOK2, ARFGAP45, AP1M1, and GPAT2—that were shared across gene sets associated with both brain function and clinical symptoms, suggesting a common transcriptional basis for these features of schizophrenia." (PMID 41271614, 2025). "An intersection analysis revealed six genes-GRK2, KLF3, TAOK2, ARFGAP45, AP1M1, and GPAT2-common to both brain function and clinical symptomatology gene sets, highlighting a shared genetic etiology in schizophrenia’s neuroimaging and clinical manifestations." (PMID 41271614, 2025).
septal defect (1 paper, 2020). "We determined that loss of GRK2 in humans results in the ATD phenotype, characterized by marked skeletal abnormalities, an atrial septal defect and significant respiratory impairment." (PMID 33200460, 2020).
steatosis (1 paper, 2016). Increased lipid within the cytoplasm of cells. "In sum, these data indicate that GRK2 protein levels increase in cardiac tissue in parallel with HFD-induced hypertrophy and steatosis, and that this increase is not detected in GRK2 hemizygous animals." (PMID 27832814, 2016).
systemic lupus erythematosus (1 paper, 2024). An autoimmune multi-organ disease typically associated with vasculopathy and autoantibody production. "In a mouse model of systemic lupus erythematosus (SLE), both genetic deficiency and pharmacological inhibition of GRK2 can mitigate histopathological alterations in the kidney." (PMID 39438268, 2024).
ulcerative colitis (1 paper, 2023). An inflammatory bowel disease involving the mucosal surface of the large intestine and rectum. "Therefore, GRK2-induced down-regulation of EP4 membrane expression may be the pathogenesis of ulcerative colitis." (PMID 37242446, 2023). "However, the role of GRK2 in the pathophysiology of ulcerative colitis (UC) remains unclear." (PMID 37242446, 2023).
viral pneumonia (1 paper, 2020). Inflammation of the lung parenchyma that is caused by a viral infection. "Moreover, XDY was suggested to improve hyperpermeability in viral pneumonia by downregulating the G protein coupled receptor kinase 2 (GRK2) protein, and upregulating β-adrenergic receptors (β-AR) and G protein (GS) α." (PMID 32957919, 2020).
cardiovascular diseases (26 papers, 2009 to 2025). "Overexpression of GRK2 is linked to cardiovascular diseases, and its inhibition or deletion has been shown to be protective." (PMID 39960030, 2025). "While the disruption of the kinase gene can be lethal in mice, GRK2 overexpression has been linked to several cardiovascular diseases in humans." (PMID 32587857, 2020). "Molecular changes and main effects associated to GRK2 overexpression in different cell types associated to cardiovascular disease." (PMID 32848782, 2020). "Similarly, alteration of GRK2 abundance and activity are associated with inflammation, cardiovascular disease, and tumors, suggesting that alterations contribute to initiation or development of pathologies." (PMID 27022742, 2016). "Overall, GRK2 is a multifaceted protein with significant implications for HF and the regulation of GRK2 is crucial for understanding and treating cardiovascular diseases." (PMID 39960030, 2025). "In this context, it is evident that GRK2 holds promise as a potential therapeutic target to attenuate the severity of cardiovascular disease." (PMID 40076919, 2025). "The main findings of these studies suggest that an increase in GRK2 is detrimental, particularly in cardiovascular disease, but there are some exceptions where it plays a beneficial role in specific tissues or conditions." (PMID 40076919, 2025). "Mitochondrial accumulation of GRK2 increases vasodilatory responses in isolated swine artery segments, indicating potential therapeutic applications for cardiovascular disorders." (PMID 40659632, 2025). "Overexpression of G-protein-coupled receptor kinase 2 (GRK2) is strongly linked to both the healthy and failing heart, and it has long been considered a therapeutic target for the treatment of cardiovascular disease." (PMID 33562229, 2021). "GRK2 levels are increased in different tissues of patients and in preclinical models of cardiovascular diseases and contribute to disease progression." (PMID 35386975, 2021). "Increased GRK2 expression in different cell types contributes to dysfunction of the heart and progression of cardiovascular disease." (PMID 32848782, 2020). "An example of a multidomain protein involved in cardiovascular disease is the G-protein coupled receptor kinase 2 (GRK2, also known as beta-adrenergic receptor kinase)." (PMID 32587857, 2020). "Among them, G-protein coupled receptor kinase 2 (GRK2) is known to favor the development of cardiovascular diseases, and recently, it has also been recognized as a modulator of mitochondrial function, including ROS production." (PMID 29201269, 2017). "Notably, several studies have demonstrated the protective effect of paroxetine as a GRK2 inhibitor in cardiovascular diseases." (PMID 38139099, 2023). "GRK2 plays a key role in the development of many cardiovascular diseases." (PMID 38139099, 2023). "Lymphocyte GRK2 levels may also serve as a biomarker for disorders other than cardiovascular disease." (PMID 33546162, 2021). "GRK2, also known as BARK, was also shown to play a role in the development of cardiovascular disease." (PMID 35890250, 2022). "Given the key role of GRK2 in the development and progression of cardiovascular diseases (CVD), including HF, targeting GRK2 could be an effective therapeutic strategy for HF." (PMID 27999776, 2016). "Three different GRK isoforms (GRK2, GRK5, and GRK3) and two β-adrenoceptors (β1-AR and β2-AR) are present in peripheral blood mononuclear cells (PBMC) and their expression changes as a consequence of the hemodynamic and neurohumoral alterations that occur in some cardiovascular diseases." (PMID 30837872, 2019).
tumor (26 papers, 2007 to 2025). "Such opposite and cellular-specific alterations in GRK2 expression seem to be causally related, promoting a marked increase of intra-tumoral hypoxia and of the tumor-associated macrophage-derived factor adrenomedullin, a known VHL-HIF-1 target gene." (PMID 32413989, 2020). "GRK2 inhibition reduces cancer cell proliferation and tumor growth by suppressing G2/M cell cycle progression and activating immune cells." (PMID 40224487, 2025). "GRK2 plays an important role in physiological and tumor angiogenesis, regulating EC activation and migration." (PMID 40224487, 2025). "The inhibition of GRK2/3 significantly slowed tumor progression and decreased markers of invasive capacity, highlighting their role in enabling cancer cells to breach local barriers and potentially metastasize to distant sites." (PMID 39940643, 2025). "Given its dual role in immune regulation and tumor biology, GRK2 emerges as a promising therapeutic target." (PMID 40224487, 2025). "The PX can release T cells sequestrated in the BM by stabilizing their surface S1PR1 receptor through the inhibition of GRK2, and increasing their infiltration in tumor." (PMID 36698265, 2023). "Of particular interest, down-regulation of GRK2 levels in endothelial cells has been found to promote tumour growth." (PMID 37686662, 2023). "In general, studies relating to these three types of tumors suggest that the downregulation of GRK2 is closely related to abnormal angiogenesis in the tumor microenvironment." (PMID 34335610, 2021). "In this regard, we hope that GRK2 can be realized in the future as a new potential anti-angiogenesis therapeutic target in tumor therapy for tumor vascular normalization, which means a decrease in the number of vessels and an increase in perfusion." (PMID 34335610, 2021). "Further, through its varied actions in lymphocytes, GRK2 influences the molecular pathogenesis of inflammatory and neoplastic disease." (PMID 33546162, 2021). "This requires in-depth exploration of the complex mechanism of GRK2 and various molecules in the tumor microenvironment in different tumor types in the future." (PMID 34335610, 2021). "In the B16F10 melanoma model, accelerated tumor progression occurs upon GRK2 downregulation, along with immature tumor vessel architecture, increased vessel perimeter, and tortuosity compared with that in wild-type (WT) mice." (PMID 34335610, 2021). "Altogether, these observations suggested a potential functional relationship between HuR and GRK2 in both tumor and non-tumor settings." (PMID 32413989, 2020). "Our results point to a relevant role of the GRK2/HuR/HIF-1α module in the adaptation of malignant cells to tumor microenvironment-related stresses." (PMID 32413989, 2020). "To explore the biological connection of GRK2 with the tumor-promoting function of eIF3d, we examined the effect of GRK2 re-expression in eIF3d knockdown stable NOZ cells on tumorigenicity." (PMID 28594409, 2017). "Downregulation of GRK2 would be a relevant event in the angiogenic switch triggered by tumor cells by favoring a permissive microenvironment for tumor progression." (PMID 27058419, 2016). "GRK2 is critical in tumor progression, exhibiting diverse effects across cancer types." (PMID 40224487, 2025). "GRK2 is a critical regulator of immune cell signaling, influencing the functional dynamics of various immune cell populations and their interactions within the tumor microenvironment." (PMID 40224487, 2025). "Third, knockdown of GRK2 in ABC-DLBCL leads to enhanced tumor growth in vivo." (PMID 33546162, 2021). "Thus, further studies are needed to elucidate the potential role of GRK2 in tumor angiogenesis by regulating macrophage infiltration." (PMID 34335610, 2021).
tumor (continued). "GRK2 is involved in T cell infiltration, while the results of previous studies suggest that GRK2 may be involved in macrophage infiltration in the tumor microenvironment." (PMID 34335610, 2021). "GRK2 affects endothelial cell proliferation and migration to regulate tumor angiogenesis." (PMID 33256128, 2020). "Moreover, we identify the inhibition of GRK2 activity as a potential strategy to delay tumor progression." (PMID 33256128, 2020). "Our in vivo findings suggest that GRK2 inhibition could be an effective strategy to delay tumor growth." (PMID 33256128, 2020). "A recent study demonstrated that the interaction of TNF-α and angiotensin II in HCC cells could enhance tumor proliferation, migration and invasion via the regulation of G protein-coupled receptor kinase 2 (GRK2)." (PMID 32722054, 2020). "Enhanced GRK2 expression and S670 phosphorylation status in the given tumor contexts would lead to enhanced HuR functionality, thus, counteracting the canonical HIF protein degradation driven by prolyl hydroxylases and recapitulating a pseudo-hypoxic state in normoxia, as a consequence." (PMID 32413989, 2020). "Given the suggested involvement of GRK2 catalytic activity in such a pathway, we explored the possibility that its inhibition could effectively delay tumor growth in vivo." (PMID 33256128, 2020). "It has been described that miR-K3, a Kaposi’s sarcoma-associated herpesvirus (KSHV) miRNA, facilitates cell migration and invasion via activation of the CXCR2/AKT pathway by repressing GRK2 expression, pointing to a role of GRK2 in suppressing KSHV-associated tumor progression." (PMID 31432234, 2019). "Furthermore, compared with WT animals, tumor vessels growing in endothelial GRK2 knockdown mice were less covered by pericytes, and the microenvironment of these tumors also exhibited a marked increase in hypoxia, adrenomedullin, and higher infiltration of macrophages." (PMID 34335610, 2021). "Therefore, GRK2 siRNA was used to examine the molecular interactions of TNF-α in tumor growth, and the obtained results suggested that TNF-α could serve as a new potential therapeutic target in HCC." (PMID 32722054, 2020). "For instance, EIF3D stabilizes GRK2 protein by blocking ubiquitin-mediated degradation, activating PI3K/Akt signaling, and promoting tumor cell proliferation and migration." (PMID 40018039, 2025). "RKIP is an endogenous tumour metastasis suppressor with detrimental cardiac effects due to RAF1-MAPK pathway inhibition and its specific mode of GRK2 inhibition." (PMID 35203304, 2022). "Taken together, RKIP exerts cardiotoxic effects by multiple pathways (i) as a tumour metastasis suppressor and inhibitor of the RAF1-MAPK axis and (ii) as a GRK2 inhibitor." (PMID 35203304, 2022). "Our results also point that the GRK2/HuR/ HIF1α axis is involved in modulating the expression of VEGF-C, a critical factor for remodeling the lymphatic network and tumor cell dissemination." (PMID 32413989, 2020). "We have shown that GRK2 mediates miR-K3-induced cell migration and invasion, implying that it might play a key role in KSHV-induced tumor dissemination and invasion." (PMID 27058419, 2016).